MCL1 (MCL1 apoptosis regulator, BCL2 family member)
Diseases named in the same sentence as MCL1 in open-access papers (continued):
Sharing a sentence is not in itself a finding about the gene and the disease.
tumor (continued). "Immunoblotting of tumor tissues revealed that treatment with apigenin or a combination of apigenin and ABT‐263 resulted in decreased expression of Mcl‐1 and reduced phosphorylation of AKT and ERK, suggesting that apigenin can also target these pro‐survival modulators in vivo." (PMID 37970406, 2023). "Notably, TCTP knockdown in A375 P3 cells increased T cell migration and sensitized tumor cells to CTL-mediated killing, which was accompanied by profound changes in CXCL10 and MCL-1." (PMID 35440620, 2022). "The expression of TRAF4 and MCL-1 were significantly upregulated in tumor tissues compared with that in paired adjacent non-tumor tissues." (PMID 36535926, 2022). "Further characterisation by matched single cell RNA-sequencing of the same tumours revealed that BCL-xL and MCL-1 expression correlated with expression of neural stem cell markers NES, SOX2 and SOX9 and the degree of malignancy within the tumours (CNA gain chromosome 7), independently of cell cycle." (PMID 35473984, 2022). "First, the Mcl-1/Bim signaling pathway was not completely elucidated in our study, although Mcl-1 and Bim are involved in initiating tumor apoptosis." (PMID 35625692, 2022). "To delineate the potential of MCL1 to limit the clinical activity of chemotherapy such as doxorubicin or oxaliplatin, we evaluated the expression of MCL1 and the related family members Bcl-2 and Bcl-xL in a large panel of CRC tumor biopsies (n = 133) by IHC." (PMID 35042842, 2022). "Investigating this apoptotic sensitivity, we found that sequential inhibition of BCL-xL and MCL-1 led to robust anti-tumour responses in vivo, in the absence of overt toxicity." (PMID 35473984, 2022). "Since IHC only measures protein quantity, it would not be able to identify the correlation between MCL-1 and tumor aggressiveness." (PMID 35221802, 2022). "AITC effectively suppressed protein expressions of MCL-1, MMP-9, VEGF, and XIAP in the tumor area." (PMID 36142326, 2022). "Overall, 2 out of 10 (20%) samples of adult patients were positive for MCL1 amplification, while no pediatric tumor showed amplification of MCL1 with the caveat that only few pediatric cases were included in our cohort." (PMID 35668118, 2022). "Further, we could demonstrate that both BCL-xL and MCL-1 are highly expressed, not only in GBM tumour cores, but also in GBM stem-like cells compared to their isogenic differentiated counterparts and astrocytes." (PMID 35473984, 2022). "Importantly, the total tumour burden for mice wild type (WT) and HET for Mcl1 was comparable at endpoint despite HET mice surviving significantly longer." (PMID 33785871, 2021). "For example, it was found that tumor cells metastasized more easily and extensively when NK cells were absent, but the role of Mcl-1 in NK cells during tumor initiation and progression remains to be determined." (PMID 34336857, 2021). "As there are potentially a very large number of solid cancers that could benefit from dual inhibition of MCL-1 and BCL-XL, a number of more tumour-specific approaches have been investigated." (PMID 33799592, 2021). "Intriguingly, we found that tumour regression was more penetrant with genetic deletion of MCL-1 rather than pharmaceutical inhibition." (PMID 33785871, 2021). "We therefore initially examined the expression of Bcl-2-, Bcl-xL and Mcl-1, of which Mcl−1 but not Bcl-2 or Bcl-xL were significantly upregulated in GBM compared with non-tumour tissue." (PMID 34344865, 2021). "In addition, the immunohistochemistry (IHC) staining revealed that ESCC tumor tissues of interfering DGCR5 group had lower expression of SRSF1 and Mcl-1 protein." (PMID 34099633, 2021).
tumor (continued). "High levels of MCL1 protein are present in respiring tumor cells but not in normal, non-cancerous respiring cells." (PMID 34831420, 2021). "However, a number of tumorigenic proteins like Bcl family, Mcl-1, survivin, IAP-1/2, COX-2, cyclin D1, VEGF, and MMP-9 can negate the apoptotic influence and promote tumor cell survival." (PMID 34360911, 2021). "Remarkably, homozygous Mcl1 deletion induced tumour regression in 8/9 Mcl1fl/fl tumours but no WT tumour regressed." (PMID 33785871, 2021). "HMAs and cytarabine can downregulate the expression of MCL1, and may exert a synergistic effect with venetoclax to interfere with the energy metabolism of AML stem cells and kill tumor cell." (PMID 33292251, 2020). "Therefore, the combination of Mcl-1 targeting and ABT-737 appears to be an efficient means of triggering apoptosis in various tumor types." (PMID 32212793, 2020). "Together these results support a tumor suppressor function for MARCH5, which may be related to its negative regulation of MCL1." (PMID 32484436, 2020). "Additionally, after Mcl-1-specific SBO treatment for 3 d, Bak, activated caspase 9, and caspase 3 expression levels in the tumor tissues were markedly elevated in a dose-dependent manner." (PMID 33052877, 2020). "MCL1, an anti-apoptotic protein of BCL2 family, is closely related to drug resistance of tumor." (PMID 33126914, 2020). "Furthermore, AZD5991 binds directly to the MCL-1 and BAK interaction and was shown to have potent antitumor activity in vivo, as demonstrated by high tumor regression in an AML xenograft model." (PMID 33251145, 2020). "Histologically, hepatocellular tumors from c-Myc/MCL1 mice consisted of small, highly basophilic cells, thus being indistinguishable from tumor lesions developed in c-Myc mice in the FVB/N genetic background, in accordance with previous findings." (PMID 33187130, 2020). "High levels of MCL-1, assessed by immunohistochemistry, could be correlated with high tumor grade, whereas low expression of MCL-1 was correlated with low tumor grade." (PMID 33308268, 2020). "Strikingly, when Mcl1∆hep mice were fed the FFC diet for 10 month the tumor incidence increased to 78%, while Mcl1-expressing (WT) mice on FFC diet did not develop any liver tumors." (PMID 32015322, 2020). "Furthermore, pre-treatment of tumor cells with BH3 mimetics resulted in an up-regulation of Bcl-2 and Mcl-1 expression in venetoclax highly sensitive 380 cells and S63845 highly sensitive U698M cells, respectively." (PMID 33362794, 2020). "However, because antiapoptotic proteins (Bcl-2, Bcl-xL, Mcl-1, c-FLIP and IAP family) are highly expressed in tumor cells, they reveal TRAIL resistance." (PMID 33050112, 2020). "However, our cell functional study revealed that tumor cell-intrinsic PD-L1 plays an anti-tumor role in multiple aggressive EC cell lines, and downregulation of PD-L1 is sufficient to stimulate the EMT features and cell invasion in an MCL-1-dependent manner." (PMID 33363153, 2020). "Combination therapy with ZA and tumor-specific replicating oncolytic adenovirus DBP-301 significantly inhibits tumor-mediated osteoclast activation, tumor growth and bone destruction via suppression of Mcl-1." (PMID 33143662, 2020). "Therefore, our data support that the sensitivity of tumor cells to BH3 mimetics increases with up-regulating expression of Bcl-2 and Mcl-1." (PMID 33362794, 2020). "We found that the expression levels of Lpl and Cd36 were equivalent in c-Myc/MCL1/Cre and c-Myc/MCL1/pCMV tumor samples, indicating the lack of a compensatory induction of the Lpl/Cd36 axis as a response to Fasn depletion in c-Myc mice." (PMID 33187130, 2020).
tumor (continued). "Significantly, while the MARCH5 mediated degradation of MCL1 markedly sensitized tumor cells to BCLXL inhibition, MARCH5 depletion, which occurs in ~5% of PCa, also sensitized to BCLXL inhibition despite increased MCL1, revealing a codependency between MCL1 and MARCH5." (PMID 32484436, 2020). "On the other hand, our data revealed that patients having tumors with MCL1 amplification had a lower baseline serum hemoglobulin, which is not always correlated well with tumor hypoxia." (PMID 32527042, 2020). "At the immunohistochemical level, c-Myc/MCL1/Cre and c-Myc/MCL1/pCMV tumor lesions displayed robust immunoreactivity for c-Myc and MCL1 with no overt differences." (PMID 33187130, 2020). "The MCL-1 inhibitor S63845 reduced viability of SCLC cell lines in vitro with an IC50 of 23 to 78 nM by inducing apoptosis, while in vivo treatment of two xenograft models reduced tumor volumes to a comparable degree as cisplatin in combination with etoposide." (PMID 33308268, 2020). "Several potent MCL1-specific inhibitors are currently being scrutinized in clinical trials for the treatment of MM and NHL, and selective BCLxL inhibitors have been designed showing significant anti-tumor activity both in vitro and in vivo." (PMID 33198338, 2020). "However, neither PIK-75 nor the other CDK7/9 inhibitors were as cytotoxic as daunorubicin against the mouse MLL-AF9 AMLs, despite reducing MCL-1 protein levels in a dose-dependent manner, even in the Mcl-1tg/MLL-AF9 tumours." (PMID 30470795, 2019). "Consequently, BRAF or MEK1/2 inhibitors are synthetic lethal with the MCL1 inhibitor AZD5991, driving profound tumour cell death that requires BAK/BAX, BIM and BMF, and inhibiting tumour growth in vivo." (PMID 31727888, 2019). "However, in tumor cells treated with ABT737, MCL-1 is a prime resistance factor, emphasizing the need for agents providing complementary function." (PMID 30538285, 2019). "Similarly, combined use of the selective Mcl-1 inhibitor VU661013 with ABT-263 resulted in tumor cell apoptosis and diminished tumor growth in vivo." (PMID 31595181, 2019). "Interestingly, molecular profiling of tumor cells treated with AMG176 showed an inverse correlation between BCL-XL expression and sensitivity to MCL-1 inhibition." (PMID 30813354, 2019). "Hence, one possible strategy to overcoming toxicities associated with targeting MCL-1 plus BCL-XL would be to exploit this potent synergy, and identify a therapeutic window where lower doses or treatment schedules might still be effective for killing tumor cells but sparing normal tissue." (PMID 31019203, 2019). "MCL-1 expression was generally higher in the tumor core and advancing front of hypopharynx, compared to the normal tissues, whereas in the larynx, MCL-1 was relatively highly expressed both in normal and tumor tissues." (PMID 31801952, 2019). "Consequently, combined inhibition of ERK1/2 signalling and MCL1 is synthetic lethal, inducing profound, synergistic BAK/BAX-, BIM- and BMF-dependent apoptosis and tumour regression." (PMID 31727888, 2019). "In conclusion, we convincingly demonstrate that BCL-XL and MCL-1 but not BCL-2 are highly expressed in tumor tissues of SCCHN patients." (PMID 31801952, 2019). "Although the MCL-1 inhibitor alone did not affect tumor growth, sequential BRAF and MCL-1 inhibition led to profound tumor regression." (PMID 31727958, 2019). "BMI-1 has been actively involved in tumor-initiating SP cells in MCL and we investigated if REC-1 SP cells are more susceptible to BMI-1 and MCL-1 reduction by PTC596 than non-SP cells." (PMID 29983879, 2018). "Interestingly, we found increased Mcl-1/Bim interactions in fulvestrant-treated MCF7 xenografts, and in clinical ERα+ tumor specimens treated with Faslodex/Arimidex." (PMID 29343814, 2018). "The tumor regression in response to H89/tetrandrine was statistically significant in the control tumors, but not in the Mcl-1 overexpressing tumors." (PMID 29866132, 2018).
tumor (continued). "Moreover, the interaction of USP13 and MCL1 occurred between endogenous proteins in A549, HEY and SW-1573 tumor cells." (PMID 29335437, 2018). "MCL-1 and BCL-xL expression were detected in 50% and 61% of the tumor samples, respectively." (PMID 30250075, 2018). "Interestingly, when we analyzed the BCL-2/MCL-1 ratio, predictive value of the observed ABT-263 efficacy, we distinguished a parallelism between tumor growth and BCL-2/MCL-1 levels among sorafenib-only treated tumors (n=11)." (PMID 29682179, 2018). "In conclusion, in this study we demonstrate that inhibition of two master regulators of cell survival, MCL-1 and BCL-2 with clinical stage drugs, voruciclib and venetoclax respectively, can achieve synergistic anti-tumor efficacy in a subset of ABC DLBCL models." (PMID 29269870, 2017). "However, the combination treatment with both MCL-1 and BCL-2 inhibitors is capable of eliminating MICs which is needed to hinder relapse potential and block tumor regeneration." (PMID 27086916, 2017). "Also IBC tumor samples showed amplifications in the following: MYC (8/32; 25%), CCND1 (7/32; 22%), ErbB2 (5/32; 16%), MCL1 (6/32; 19%), and FGFR1 (3/32; 9%)." (PMID 28271309, 2017). "TG02 has a wide range of potential mediators of its anti-tumour activity, and we do not assume that MCL-1 is the single mechanistic target for TG02." (PMID 27092880, 2017). "This characterises TrkAIII SH-SY5Y cells as type I tumour cells, sensitive to TRAIL-induced apoptosis through the extrinsic pathway, with the intrinsic pathway blocked by constitutive Bcl-2, Bcl-xL and Mcl-1 expression (this study and 49)." (PMID 27821809, 2016). "On the other hand, coordinate down-regulation of MCL-1 and JAK3 in T cells from RCC patients could represent a mechanism of immune evasion which confers a survival advantage to the tumor in the face of a muted attack by the immune system." (PMID 27063186, 2016). "To directly address miR-29b and miR-198 specificity and MCL-1 and JAK3′s involvement in tumor suppressor activity, we investigated the effect of both miRNAs inhibition on apoptosis, as induction of immune cell apoptosis is a crucial event during malignant transformation." (PMID 27063186, 2016). "Cyclin E depletion in various human tumor cell-lines and cyclin E−/− mouse embryo fibroblasts showed decreased levels of Mcl-1 protein, with no change in Mcl-1 mRNA levels." (PMID 26219338, 2015). "Additionally, Mcl-1 expression was inhibited by targeting of the mTOR pathway using the rapalouge RAD001/everolimus, promoting increased tumor cell killing in in vivo models of colon cancer." (PMID 25784482, 2015). "Interestingly, the addition of an mTOR inhibitor to BH3 mimetics reduces the expression of the antiapoptotic protein Mcl-1 and allows high BIM levels to “prime” tumour cells for apoptosis." (PMID 26639561, 2015). "Contrary to other tumor cell contexts, MCL-1 expression in GCB-DLBCL cells did not decrease following PI3K/mTOR inhibition." (PMID 26460954, 2015). "As a consequence, the combination of TRAIL and CDK9 inhibition is exquisitely powerful in killing tumor cells with a cFlip-imposed block to initiator caspase activation at the DISC and an Mcl-1-imposed block to activation of the mitochondrial apoptosis pathway." (PMID 24362439, 2014). "Therefore, the simultaneous targeting of MCL1 and BCL-2/BCL-XL is required to increase the apoptotic cell death of tumor cells." (PMID 24523919, 2014).
tumor (continued). "We also identified a positive correlation in the expression of β-catenin and Mcl-1 in both GIST tumor specimens and GIST cell lines, suggesting that β-catenin may be an effector of OPN-mediated up-regulation of Mcl-1 and anti-apoptosis in GIST." (PMID 24947165, 2014). "Our observations emphasize the necessity to investigate Mcl-1 expression levels prior to the therapeutic utilization of TRAIL in GBM patients, especially when one considers the high levels of Mcl-1 expression reported in tumours isolated from such patients." (PMID 24213561, 2014). "We also observed that transfection EZH2, MCL-1 and FOS siRNA significantly inhibited the ability of SPAC-1-L and HEC-50 cells to invade and to form spheres, mimicking the tumor suppressive effects upon miR-101 overexpression." (PMID 25153722, 2014). "Dinaciclib induction of tumor cell apoptosis was also observed in vivo in MCL1:BCL-xL high ratio tumors, but not in low ratio tumors." (PMID 25289887, 2014). "TRAIL-R3, Bcl-xL and Mcl-1 showed no differential expression in tumor tissue compared to normal tissue." (PMID 24209510, 2013). "They used USP9X knockdown in combination with ABT-737, a small molecule antagonist of the pro-survival proteins not including MCL1 to test increased apoptosis in tumor cells." (PMID 24152793, 2013). "While the role of miR-204 as a tumor suppressor is well established, its ability to regulate Mcl-1 expression was not known prior to this study." (PMID 24025188, 2013). "Evaluation of Mcl-1 expression in human patient tumors show higher levels of Mcl-1 in tumor tissue compared to the adjacent normal tissue as well as normal pancreas." (PMID 24025188, 2013). "To this end, we found that in WT-Fbw7 genetic backgrounds, loss of the PTEN tumor suppressor, which leads to inactivation of GSK3 kinase, also results in elevated Mcl-1 expression in a similar fashion to Fbw7-deficiency (data not shown)." (PMID 21608150, 2011). "Because ABT-737 does not block Mcl-1, it is anticipated that this drug will be most effective as a single agent against tumours that express low levels of these pro-survival protein." (PMID 21854558, 2011). "Moreover, there are now a number of reports showing that proteasome inhibitors can sensitize tumour cells to ABT-737, which indicates that they neutralize Mcl-1." (PMID 20576107, 2010). "In a number of cells it has been demonstrated that it is the expression of Mcl-1 that determines resistance to ABT-737 while A1 has been suggested not to be expressed by most tumours." (PMID 20576107, 2010). "Based on the quantitative RT-PCR experiments presented in this study, a potential source of functional redundancy is Bcl-w, which appears to be expressed at significantly higher levels than Bcl-2, A1, Mcl-1 and Boo in both normal islets and lesional stages of the RIP1-Tag2 tumor pathway." (PMID 19209227, 2009). "Importantly, we previously reported that MCL1, IFITM1, and USP18 are co-expressed with STAT1 in the IR- and IFN-resistant nu61 tumor." (PMID 19503789, 2009). "The ABT-737 molecule, which does not bind Mcl-1 and A1, and which therefore has a binding profile similar to that of Bad, exhibits single-agent cytotoxicity in select tumour models as described." (PMID 19079626, 2008). "Consistent with the in vitro results, tumor growth was impeded by MCL1 depletion and HK2 overexpression partially restored the growth of MCL1-depleted tumors, suggesting a role for modulation of HK2- mediated bioenergetics in the tumor-promoting effects of MCL1." (PMID 41326406, 2025).